CAV1 (caveolin 1)
Diseases named in the same sentence as CAV1 in open-access papers (continued):
Sharing a sentence is not in itself a finding about the gene and the disease.
breast carcinoma (continued). "Here, we investigated CAV1’s role in cellular compartments of breast cancer in relation to signaling pathways, clinicopathological features, and clinical outcomes." (PMID 35660849, 2022). "CAV1 (Caveolin 1) is a multifunctional membrane protein that promotes migration and invasion of tumor cells and is a multifaceted driver of breast cancer progression." (PMID 36143471, 2022). "Although the HOTAIR/miR-203/CAV1 network is of great significance to the progression of breast cancer in MDA-MB-231, what other regulators are involved?" (PMID 36233075, 2022). "Alternatively, MDA-MB-231 human breast cancer cells that express high endogenous CAV1 levels were transduced with an shRNA to knock down CAV1 (shCav1) or with a control shRNA (shScr)." (PMID 35740528, 2022). "If only the overexpression of HOTAIR or overexpression of CAV1, or the inhibition of the expression of miR-203 is considered, the proliferation, invasion, and migration of breast cancer MDA-MB-231 cells can be significantly improved." (PMID 36233075, 2022). "In line with our data, reports show downregulation of CAV1 as an important step in breast cancer development and resistance to endocrine therapies." (PMID 35401937, 2022). "Upregulation of CAV-1 enhances the sensitivity of HER2-positive breast cancer cells to T-DM1 by promoting endocytosis of trastuzumab." (PMID 36210846, 2022). "We have shown that OCT-1 knockdown suppresses the expression of the ARHGDIB, CAPZA2, PHACTR2, CDC42, XRCC5, and CAV1 genes, which is known to be increased in actively metastasizing breast cancer cells." (PMID 36143471, 2022). "This further inspires us to explore the miRNA that can connect lncRNAHOTAIR and CAV1 and improve the role of the ceRNA/mRNA network in the progression of breast cancer." (PMID 36233075, 2022). "Experimental studies have shown that CDKN2A, PSAT1, HMGB1, ELAVL1, and SLC7A11 were up-regulated in TNBC, ASNS and LAMP2 were up-regulated in breast cancer and CAV1 was down-regulated in breast cancer, and HELLS was up-regulated in other tumors." (PMID 36568247, 2022). "When CAV1 was overexpressed in HER2-positive breast-cancer cells, the cells were more sensitive to T-DM1 treatment." (PMID 35158857, 2022). "In this study, the down-regulation of CAV1 expression attenuated the proliferation, invasion, and migration of the breast cancer cell MDA-MB-231." (PMID 36233075, 2022). "Addressing these key issues would further corroborate the mechanism of CAV-1 in breast cancer progression." (PMID 36604141, 2022). "To summarize, our study demonstrates how CAV-1 downregulation affects the invasiveness and metastasis of breast cancer cells." (PMID 36604141, 2022). "According to the study by Shiet al., the downregulation of CAV-1 in cocultured fibroblasts can promote proliferation and inhibit the apoptosis of breast cancer cells (BCCs)." (PMID 36604141, 2022). "Collectively, the positive rate of CAV-1 expression in breast cancer tissues was 20%, which indicated lymph node metastasis." (PMID 36604141, 2022). "Regulation of vinculin tension in MDA-MB-231 breast cancer cells is therefore both CAV1- and Gal3-dependent." (PMID 33833286, 2021). "In the next step, we established a xenograft mice model to confirm that the effect of Doxo and HCQ combination in CAV1 downregulated breast cancer cells." (PMID 34786475, 2021). "In vivo and in vitro studies demonstrated Nrf2-driven MnSOD upregulation postulated from degradation of Caveolin-1 resulted in enhanced cell survival, metastasis, and drug resistance in circulating breast cancer cells." (PMID 34490076, 2021). "In the present study, we also delineated the molecular mechanism of ursolic acid-induced Cav-1 up-regulation in breast cancer cells." (PMID 34568078, 2021). "This research identified MMPs and EMT pathways, especially caveolin 1 (Cav-1), as the primary targets to inhibit breast cancer metastasis." (PMID 33801741, 2021).
breast carcinoma (continued). "Immunoblot analyses in AG1522 CAFs cocultured with MDA-MB-231 or MCF7 breast cancer cells under ambient conditions confirmed the decrease in Cav-1 detected by mass spectrometry." (PMID 33637118, 2021). "Corresponding to these findings, CAV-1 was found to be overexpressed in drug-resistant breast cancer cells." (PMID 33816265, 2021). "The expression levels of CAV1 mRNA were significantly downregulated in patients with breast cancer in 31 datasets." (PMID 34513683, 2021). "This is further supported by the finding that CAV1 protein levels are almost undetectable in most breast cancer cell lines (except for MDA-MB-231 cells)." (PMID 34786475, 2021). "Cav-1 is involved in the oncogenesis and development of various malignancies, such as colon, ovarian, lung and breast carcinoma." (PMID 34168559, 2021). "In a retrospective study regarding breast cancer patients, the Cav-1-positive group showed 72 months of cancer-specific survival, whereas the survival time of the Cav-1-negative group was 29.5 months." (PMID 33614646, 2021). "For example, salvianolic acid B was reported to ameliorate lipopolysaccharide-induced albumin leakage from rat mesenteric venules by binding to Src, Astragaloside IV was shown to enhance taxol chemosensitivity of breast cancer by targeting caveolin-1." (PMID 34975519, 2021). "This study not only highlights ursolic acid as a promising candidate drug for breast cancer treatment but also sheds novel light on Cav-1 as a druggable target for glycolytic modulation of breast cancer." (PMID 34568078, 2021). "This process involves AS-IV activation of eNOS/NO/ONOO− signaling by CAV-1 inhibition that enhances the chemosensitivity of breast cancer cells to paclitaxel." (PMID 33816265, 2021). "To address this question, we established a doxycycline (Dox)-inducible CAV1 KD MDA-MB-231 cell line (the only breast cancer cell line we tested with normal CAV1 expression) and confirmed that the basal autophagy level is indeed promoted by CAV1 deficiency." (PMID 34786475, 2021). "More importantly, Cav-1 knockdown partly abrogated the inhibitory effects of ursolic acid on that in breast cancer cells." (PMID 34568078, 2021). "In high metastatic breast cancer cells, CAV1 mediates the loading of adhesion-related proteins into EVs, promoting migration and invasion of recipient cells." (PMID 34222256, 2021). "Altogether, ursolic acid impairs the glycolytic metabolism of breast cancer cells by activating SP1/Cav-1 signaling." (PMID 34568078, 2021). "Recent studies have shown that the HIF-1α–Cav-1 signaling axis mediates autophagy to regulate cellular metabolism and promote the survival and metastasis of breast cancer cells." (PMID 34955837, 2021). "For example, Cav-1 expression was restored in breast cancer CAFs upon treatment with chloroquine, which is an antioxidant and autophagy inhibitor." (PMID 34769066, 2021). "Mir-221/222-induced deregulation of CAV1 represents a key pathway involved in breast cancers’ invasion, migration, and metastasis." (PMID 34199293, 2021). "This study not only highlights ursolic acid as a promising candidate drug for breast cancer treatment but also sheds new insights on Cav-1 as a druggable target for glycolytic modulation of breast cancer." (PMID 34568078, 2021). "This study not only provides preclinical evidence supporting the application of ursolic acid as a promising candidate drug for breast cancer treatment but also sheds novel light on Cav-1 as a druggable target for glycolytic modulation of breast cancer." (PMID 34568078, 2021). "In this study, the interaction between Hif-1α and Cav-1 was investigated during autophagy-mediated metastasis in breast cancer." (PMID 33381039, 2020). "A 4-Gy X-ray irradiation increased the proportions of G2/M phase and Caveolin-1 content in 4T1 breast cancer cells, contributing to an endocytic enhancement of PINPs@PM." (PMID 32690018, 2020).
breast carcinoma (continued). "What is more, our previous study identified betulinic acid as an inducer of Cav-1 expression in breast cancer cells." (PMID 32528105, 2020). "Herein, betulinic acid treatment significantly elevated Cav-1 expression whereas attenuated the stemness-related protein ALDH1A1 in mammary tumors of MMTV-PyVT+/- breast cancer spontaneous mice." (PMID 32528105, 2020). "Taken together, our data show that SA inhibited Cav-1 levels to block late-phase autophagy and subsequently delay breast-cancer progression under hypoxic stress." (PMID 33381039, 2020). "Studies have reported that an elevated expression of Cav-1 in the stroma of breast cancer patients confers significant protection against progression to metastases and associates with increased chances of survival." (PMID 32633727, 2020). "In breast cancer, synaptopodin-2 and caveolin-1 have been shown to modulate Akt/mTOR-regulated metastatic progression." (PMID 32615541, 2020). "Caveolin-1 (CAV-1) is a protein predictive in human breast cancer prognosis; downregulation of CAV-1 induces metabolic reprogramming of CAFs and indicates poor prognosis in breast cancer." (PMID 33322749, 2020). "Metformin induces CAV1 expression, which in return increases clinical efficacy of drug delivery (trastuzumab emtansine) in breast cancer cells." (PMID 32082483, 2020). "Evidence from our laboratory also described the possible role of CAV1 in EVs derived from the metastatic human breast cancer cell line MDA-MB-231." (PMID 32458269, 2020). "Another report focused on the role of CAV1 in the treatment of human EGFR2 (HER2)-positive breast cancers." (PMID 32458269, 2020). "Specifically, these authors showed that CAV1 colocalizes with the drug in SKBR-3 breast cancer cells that express moderate levels of the protein." (PMID 32458269, 2020). "Previous studies analyzing CAV1 knockout mice and stroma from breast cancer patients revealed that increased HIF1α target gene expression correlated with reduced CAV1 levels." (PMID 32825247, 2020). "We further demonstrated that SA inhibited breast cancer metastasis primarily by restraining late-stage autophagy via Hif-1α/Cav-1 signaling." (PMID 33381039, 2020). "In metastatic breast cancer and melanoma cells, CAV1 phosphorylation on Y14 increases cell migration by promoting focal adhesion turnover, polarization, persistency, speed, and directionality of migration." (PMID 32152405, 2020). "Altogether, breast cancer cells exhibit decreased expression of Cav-1, as well as reprogrammed metabolic patterns, shifted from mitochondrial respiration to aerobic glycolysis." (PMID 32528105, 2020). "Treatment with a DNA methyltransferase inhibitor in breast cancer cell lines leads to the re‐expression of Cav‐1 through demethylation of CpGi shores." (PMID 32508059, 2020). "To further evaluate this possibility, we focused on two metastatic cell models lacking E-cadherin, B16F10 murine melanoma cells that lack CAV1 expression and MDA-MB-231 human breast cancer cells with high endogenous levels of CAV1." (PMID 32811828, 2020). "For instance, in breast cancer, caveolin-1 was found to cololocalize with MT1-MMP at the invadopodia mediating breast cancer cell invasion." (PMID 33150941, 2020). "For example, in doxorubicin-resistant Hs578T breast cancer cells, Cav-1 over-expression can reduce the activity of P-gp and corresponding doxorubicin resistance." (PMID 31991790, 2020). "Regarding the tumour suppressor function of CAV1, its expression is inhibited in several human tumours, including lung, breast cancer, ovarian cancer and osteosarcoma." (PMID 32606289, 2020). "Intriguingly, Cav-1 is widely considered a tumor suppressor, and low expression of Cav-1 in surrounding adipocytes drives tumor growth and metastasis in breast cancer." (PMID 32411704, 2020). "Since then, numerous data have been collected from cell lines involving both Cav-1 and -2, [colon carcinoma, human breast cancer, and ovarian carcinoma], or only Cav-1." (PMID 33195223, 2020).
breast carcinoma (continued). "Our pilot study also demonstrated that Cav-1 acts as the upstream regulator of NF-κB in breast cancer." (PMID 33381039, 2020). "Some studies have found that CAV1 is involved in liver cancer, colon cancer, breast cancer, kidney cancer, lung cancer and other cancers, and acted as a promoter or inhibitor of cancer according to the type and stage of cancer." (PMID 32547947, 2020). "Our study sheds novel light on Cav-1 targeted metabolic modulation as a promising strategy for breast cancer treatment via BCSCs elimination." (PMID 32528105, 2020). "Although there were different epigenetic changes in Cav‐1 among breast cancer subtypes, for example, CAV1 was overexpressed after being hypomethylated in inflammatory breast cancer." (PMID 32508059, 2020). "A relative deficiency of caveolin-1 (CAV1) in tumor-associated fibroblasts has been postulated to underlie the reverse Warburg effect, in which cancer cell oxidants downregulate CAV1 in stromal fibroblasts that are tumorigenic in breast cancers." (PMID 32841217, 2020). "Meanwhile, the proportion of ALDH+ BCSCs in mammary tumors of MMTV-Wnt1/Cav-1+/− mice was significantly higher than that of MMTV-Wnt1 mice (P < 0.01)." (PMID 32528105, 2020). "Our present study indicated that Cav-1 knockdown in mammary-tumor-prone mice was also accompanied by accelerated onset and growth of mammary tumors." (PMID 32528105, 2020). "CAV1 deficiency can induce autophagy in HCC, while CAV1 was also reported to promote autophagy and inhibit apoptosis in breast cancer cells." (PMID 32082178, 2019). "We recently described a novel Caveolin-1(CAV1)/Ras-related protein 5A (Rab5)/Ras-related C3 botulinum toxin substrate 1 (Rac1) signaling axis that promotes metastasis in melanoma, colon, and breast cancer cells." (PMID 31484460, 2019). "Here, we show that AT2R activation decreases CAV1-enhanced melanoma and breast cancer migration and invasion." (PMID 31484460, 2019). "Breast cancer cells-derived exosomal caveolin-1 (CAV1) can facilitate migration and invasion of cells with knockout of CAV1 in vitro." (PMID 31355262, 2019). "Except for breast cancer, expression of Cav-1 contributes to tumor growth and metastasis through inhibiting autophagy in hepatocellular carcinoma." (PMID 31759347, 2019). "The role of Steroid receptor coactivator-1 (Src-1) and Caveolin-1 (Cav-1) genes in tumor progression and lung metastasis of breast cancer was observed in MMTV-PyMT mice model." (PMID 30781353, 2019). "Cav1 levels in these cell lines were previously shown to be similar to endogenous Cav1 levels in MDA-MB-231 breast carcinoma cells." (PMID 31803361, 2019). "Obviously, we can see that NF1, BRCA1, FOXO1, PTEN, CAV1 and WT1 are linked with breast cancer genes in PPI network or pathway network." (PMID 31760937, 2019). "In this study, we detected the expression of CAV1 among a series of breast cancer and normal mammary cell lines." (PMID 30333750, 2018). "To rule out a cell-specific effect on YAP-CAV1 functional interactions, we used small interfering RNA (siRNA) duplexes to transiently knock down CAV1 in epithelial MDA-MB-231 human breast carcinoma cells." (PMID 30404014, 2018). "Decreased tumor Cav-1 mRNA level is associated with low ER and PR and high HER2 expression in breast cancer, which is consistent with our study." (PMID 30348118, 2018). "This study is the first to demonstrate a role for tumor/stromal Cav-1 in breast cancer as a predictive biomarker for efficacy outcomes of nab-paclitaxel and gemcitabine." (PMID 30348118, 2018). "Given the emerging role of caveolin-1 in breast cancer progression, our findings raise the possibility of exploiting caveolin-1 as a therapeutic target to prevent invasion or as a clinical biomarker." (PMID 29331414, 2018).
breast carcinoma (continued). "As a proof of concept, a previous study showed that inhibition of caveolin-1 signalling by siRNA or caveolin scaffolding peptide in inflammatory breast cancer cells resulted in a reduction in invasive potential in an Akt1-dependent manner." (PMID 29331414, 2018). "The expression of caveolin-1 is also reduced in many primary tumors, such as colorectal cancer, ovarian cancer, and breast cancer." (PMID 30424755, 2018). "For example, it was shown that quercetin reversed tamoxifen resistance in breast cancer cells, and its metabolites likely suppressed CAV1 expression." (PMID 30333750, 2018). "UMUC14 bladder, NCIN87 gastric, BT474 and SKBR3 breast cancer cell lines exhibited the highest ratio of HER2-to-CAV1 protein levels and were chosen for use in subsequent in vitro and in vivo experiments." (PMID 30510281, 2018). "Whilst highly predictive of survival in breast cancer, low stromal Cav-1 has only recently been shown to be of prognostic significance in NSCLC." (PMID 29416729, 2018). "In a number of cancer types including ovarian, colon and breast cancer, CAV1 was found to be downregulated." (PMID 29719615, 2018). "Caveolin-1 is highly expressed in invasive breast cancer cells consistent with reports linking caveolin-1 expression with tumour aggressiveness and poorer prognosis and more recently caveolin-1 has been shown to play a role in EMT." (PMID 29331414, 2018). "A cross-cancer effect is present for the histotypes breast cancer and gastric cancer as classes toSTAD and toTHCA show overlapping characteristic proteins Cyclin_B1 and Caveolin-1 (p = 0.02) for those two histotypes." (PMID 30442178, 2018). "ADQ synergistically interacted with paclitaxel to suppress MCF-7 cell proliferation, whereas CAV1 overexpression obviously abrogated the synergistic effects of ADQ with paclitaxel in suppressing breast cancer growth (p ≤ 0.01)." (PMID 30333750, 2018). "We assessed Cav-1 expression of breast cancer tissue and stromal tissue through immunohistochemistry and set the cut-off point as median value of scores." (PMID 30348118, 2018). "Our data raise concerns regarding targeting the FASN/ERα signalling pathway in ERα-positive breast cancers as inhibiting them enhanced the invasive potential of the cells via a novel caveolin-1-dependent mechanism." (PMID 29331414, 2018). "This phenomenon was consistent with the oncogenic and tumor suppressor roles of CAV1 in breast cancer development." (PMID 30333750, 2018). "On the contrary, rescued Cav-1 expression in a breast cancer cell line suppressed Nrf2 and downregulated MnSOD." (PMID 29670683, 2018). "Our results also demonstrated that CAV1 expression was highly elevated in paclitaxel-resistant breast cancer cells, and ADQ chemosensitized breast cancer cells by inhibiting CAV1, consistent with the oncogenic role of CAV1." (PMID 30333750, 2018). "One possible explanation is that high stromal Cav-1 levels allow for increased nab-paclitaxel uptake in stromal cells and tissue, which competitively reduce the uptake of nab-paclitaxel in the breast cancer cells." (PMID 30348118, 2018). "We showed that, upon portal vein injection of E0771 breast cancer cells, metastatic growth and vessel density of liver metastatic lesions was unaffected upon BM deletion of Cav1." (PMID 29212030, 2017). "In breast cancer, cav-1 is frequently down regulated in fibroblasts of patient breast tumors and has been associated with a more aggressive tumor signature." (PMID 28187162, 2017). "Treatment of these cells with 5-aza dideoxycytidine (Deoxy, 5 μM), a DNA methylation inhibitor, increased CAV1 expression both in colon and breast cancer cell lines." (PMID 29340103, 2017). "For example, Cav-1 was found upregulated in multidrug-resistant colon cancer cells, adriamycin-resistant breast cancer cells, and taxol- and gemcitabine-resistant lung cancer cells." (PMID 28546853, 2017).